MGMT (O-6-methylguanine-DNA methyltransferase)
Diseases named in the same sentence as MGMT in open-access papers (continued):
Sharing a sentence is not in itself a finding about the gene and the disease.
glioblastoma (continued). "Clinically, MGMT promoter methylation correlates with increased sensitivity to TMZ and longer overall survival, particularly in secondary glioblastomas where methylation is more prevalent (∼ 75 %) compared to primary glioblastomas (∼ 36 %)." (PMID 41311621, 2025). "A range of prognostic factors have been identified for patients with glioma WHO grade III and glioblastoma, including age, WHO PS, extent of surgery, postoperative treatment, O-6-methylguanine-DNA methyltransferase (MGMT) methylation status, and isocitrate dehydrogenase (IDH) mutation." (PMID 39827416, 2025). "Indeed, in our previous study we showed that expression of MGMT, the main regulator of TMZ resistance in glioblastomas remained unchanged after treatment." (PMID 41590784, 2025). "Randomized trials have demonstrated that elderly patients with MGMT-methylated (IDH-non-specified) glioblastoma achieve superior survival with TMZ alone compared to radiotherapy alone without increasing toxicity." (PMID 41346390, 2025). "Intriguingly, EXO1 deficiency does not lead to TMZ resistance in TK6 cells and instead somewhat hyper-sensitizes to TMZ, which is in disagreement with the result of CRISPR-based genome-wide screen carried out in TMZ-treated MGMT-negative glioblastomas." (PMID 39656916, 2025). "Consequently, the MGMT promoter methylation status serves as a predictive biomarker for TMZ response, in particular in elderly patients with newly diagnosed glioblastoma." (PMID 40244270, 2025). "Although not as extensively studied in glioblastoma as MGMT methylation, the co-deletion of chromosome arms 1p and 19q (1p/19q co-deletion) is also observed in gliomas and in approximately 7–12% of glioblastomas." (PMID 40072074, 2025). "We found that the high-risk group was strongly linked with older age, GBM (glioblastoma, WHO grade 4), IDH-wildtype, 1p/19q non-codeletion, MGMT promoter unmethylation and classical or mesenchymal subtypes (p < 0.001)." (PMID 39121828, 2024). "In the majority of glioblastoma/glioma studies, high NLR was established as an independent factor for worse outcomes without including MGMT promoter methylation status, steroid use, IDH mutation status, or other prognostic variables in multivariate analyses." (PMID 38481999, 2024). "Therefore, we used Glioblastoma IDH wildtype 4 patient-derived glioma stem-like cells and commercial adherent cells with a varied MGMT promoter methylation status to evaluate PU-H71’s activity against glioma cell proliferation." (PMID 39682123, 2024). "Methylated MGMT status are predictors for better overall survival in unresectable IDH wildtype glioblastoma patients undergoing biopsy and treatment regardless of the treatment modality." (PMID 39367282, 2024). "Finally, the DNA methylation status of O6-methylguanine-DNA methyltransferase (MGMT) is widely used as a predictive biomarker for therapeutic response to the alkylating agent, temozolomide, and as a prognostic marker in glioblastoma patients." (PMID 38183103, 2024). "O6‐methylguanine‐DNA methyltransferase (MGMT) silencing is a validated biomarker in glioblastoma but has not been deeply investigated in pancreatic cancer (PAC)." (PMID 39618336, 2024). "Subsequent investigations revealed that SFN chemosensitized U87-R and U373-R glioblastoma cell lines to TMZ by mechanistically suppressing NF-κB activity and O6-methylguanine-DNA methyltransferase (MGMT), and by modulated expressions of caspases, resulting in decreased cell proliferation." (PMID 38254735, 2024). "PRMT5 gene dysregulation can occur in IDH-mutant WHO-G4 astrocytomas and IDH-wildtype glioblastomas, regardless of MGMT-promoter status." (PMID 38827324, 2024). "This may, in conjunction with our data on MGMT and MMR genes, elucidate the pivotal role of PDCD10 in mediating TMZ sensitivity in glioblastoma." (PMID 39273014, 2024).
glioblastoma (continued). "These discrepancies indicate that while CEST/APT imaging shows potential in distinguishing MGMT methylation status in glioblastoma, the results are not yet definitive." (PMID 39148521, 2024). "The keywords included were: (Glioblastoma AND MGMT AND Machine Learning AND Artificial Intelligence), (Gliomas AND MGMT AND Machine Learning AND Deep Learning), and (MGMT AND (Machine Learning OR Deep Learning OR Artificial Intelligence OR Radiomics OR Radiogenomics) AND (gliomas OR glioblastomas))." (PMID 38291266, 2024). "Studies have also demonstrated that patients with MGMT promoter methylated glioblastomas have a significantly longer overall survival regardless of treatment." (PMID 39767640, 2024). "Its aim is to improve the poor overall survival (OS) of patients with methylguanine methyltransferase (MGMT) non-methylated glioblastoma without increasing toxicity." (PMID 38765202, 2024). "Evidently, there is no obvious radiological phenotype related to MGMT promoter methylation in glioblastomas, and both methods and results of previous studies varied considerably." (PMID 39531176, 2024). "APNG had the potential to serve as a therapeutic target and provided a new clue to explain why MGMT‐negative glioblastoma is resistant to TMZ." (PMID 38332576, 2024). "After receiving TMZ therapy, patients with methylation MGMT promoters for glioblastoma multiforme fared better than those without such a promoter." (PMID 38817857, 2024). "We separately analyzed patients who were reclassified as glioblastoma, and there was still no benefit with the addition of chemotherapy regardless of MGMT status." (PMID 38672254, 2024). "The deep learning model based on MRI data can effectively distinguish between glioblastoma patients with and without MGMT promoter methylation." (PMID 39716317, 2024). "In this study, we identified that MGMT methylation impacted on the overall survival of inoperable IDH-wildtype glioblastoma undergoing systemic treatment, regardless of the treatment modality." (PMID 39367282, 2024). "Patients with glioblastoma and unmethylated MGMT promoters did not have improved survival when temozolomide was added to radiation treatment." (PMID 38817857, 2024). "It enhances TMZ cytotoxicity in MGMT-positive but not in MGMT-negative glioblastomas in vitro, but the required concentration (20 mM) is very high, and clinical studies were unsuccessful." (PMID 39011394, 2024). "Recently, long-term survival (more than three years) in glioblastoma was not correlated to MGMT methylation status, usually considered a strong prognostic indicator, but to an increased endothelial invasion of the core." (PMID 39513861, 2024). "An excellent example is the N2M2 study in patients with newly diagnosed glioblastoma without methylation of the O6-methylguanine-DNA methyltransferase (MGMT) promoter, a phase I/IIa umbrella trial of molecularly matched targeted therapies." (PMID 39316248, 2024). "Nevertheless, baseline NLR was still prognostically independent of MGMT promoter methylation status, IDH mutation status, and steroid use in patients with glioblastoma, and patients with increased NLR and requiring steroids had the poorest outcomes." (PMID 38481999, 2024). "In conclusion, deep learning features of glioblastoma, especially the combination of T1WI and CE-T1WI, could reflect tumor molecular pathology indicators of MGMT methylation status." (PMID 39716317, 2024). "Because LN229 has a high level of DNA methylation in the promoter of MGMT (82.7% by pyrosequencing analysis), we examined the effect of TUG1 ASO and TMZ in another glioblastoma cell line U251MG, which has a lower level (23.2%) of DNA methylation in the MGMT promoter." (PMID 37607907, 2023).
glioblastoma (continued). "In total, 36 patients with glioblastoma, IDH wildtype, WHO Grade 4 (determined via immunohistochemistry), were identified at the UC Davis Neuro-Oncology clinic (18 MGMT methylated, 16 MGMT unmethylated, 2 MGMT status unknown)." (PMID 36837918, 2023). "The amount of O6MeG increases linearly with dose in MGMT-lacking glioblastoma cells, and the DNA damage response is activated to the same extent." (PMID 38068493, 2023). "Neuropathological examination revealed a glioblastoma, IDH-wildtype, MGMT-promoter methylated." (PMID 37561227, 2023). "CheckMate 498 was a randomized phase III study investigating the efficacy of nivolumab and radiation compared with conventional chemoradiation in patients with newly diagnosed glioblastoma with negative MGMT promoter methylation." (PMID 36874119, 2023). "Although IHC has not been validated in glioblastoma due to a number of limitations, we performed an exploratory evaluation of MGMT protein expression by IHC where possible." (PMID 37371106, 2023). "In conclusion, the evidence available to date, although scarce and based on glioblastoma patients, is that, despite its simplicity, MGMT determination by IHC is not sufficiently reliable for basing management decisions upon." (PMID 36826067, 2023). "Neuropathological examination confirmed the diagnosis of a glioblastoma multiforme, MGMT-promoter not methylated." (PMID 37561227, 2023). "Common prognostic indicators of glioblastoma include Karnofsky performance status (KPS), age, extent of tumor resection, radiotherapy, chemotherapy, tumor size, tumor location, and molecular profiling for biomarkers such as IDH1, EGFR, PTEN, and MGMT." (PMID 37899778, 2023). "Pathology revealed gliosarcoma (a rare variant of glioblastoma), WHO grade IV, negative for O6-methylguanine-DNA methyltransferase (MGMT) promoter methylation." (PMID 37654948, 2023). "Given that, our research team conducted several studies concerning the prognostic significance of semi-quantitative MGMT promoter methylation status obtained with both conventional MSP and Real-Time MSP assays among the Serbian population of glioblastoma/diffuse glioma patients." (PMID 36766464, 2023). "We suggested that the increased transcription of BRCA1, ATM, and DNA-PK might counteract the MGMT depletion induced by AE and TMZ treatment of glioblastoma cells." (PMID 37630276, 2023). "We next examined a balanced glioblastoma cohort of STS and LTS by excluding patients with the greatest confounding clinical variable (partial resection) and controlled for other variables that affect survival, such as MGMT methylation status." (PMID 36725935, 2023). "Neuropathological examination revealed a glioblastoma, IDH-wildtype, MGMT-promotor methylated." (PMID 37561227, 2023). "In IDH wildtype glioblastomas (GBM), MGMT status was the only significant predictor." (PMID 37242509, 2023). "O6-methylguanine-DNA methyltransferase (MGMT), a DNA repair enzyme and downstream effector of the HH cascade, has been reported to significantly contribute to the development of drug resistance in both glioma and glioblastoma." (PMID 37510333, 2023). "An alternative strategy of tumor sensitization through MGMT inhibition is based on targeting bromodomain and extra-terminal tail (BET) proteins, which have been identified as potential epigenetic targets in cancer, including glioblastoma." (PMID 38068493, 2023). "The typical application of radiomics methods in glioblastoma imaging is a differential diagnosis (with other tumors, pseudoprogression), survival prognosis in general life expectancy, identification of molecular biomarkers (for example, IDH1, MGMT)." (PMID 37388754, 2023). "In the case of iPDT-treated recurrent glioblastomas, no survival benefit was found for a methylated MGMT promoter compared to an unmethylated MGMT promoter." (PMID 37174068, 2023).
glioblastoma (continued). "Moreover, new and more aggressive therapies of glioblastomas have been introduced, e.g. the adjuvant and concomitant temozolomide and CCNU chemotherapy for patients with MGMT promoter methylated glioblastoma as well as the tumour-treating fields." (PMID 38032426, 2023). "That the 06-MeG temozolomide-induced adduct is the most prominent lesion is indirectly demonstrated by the evidence that glioblastomas with the reduced or absent activity of the MGMT enzyme are more sensitive to the drug." (PMID 35806153, 2022). "Combined treatments were also successful against pediatric preclinical models with low MGMT expression (i.e., GBM2 glioblastoma and Rh28 rhabdomyosarcoma), responsive to temozolomide, and those with a defective homologous recombination, responsive to talazoparib (i.e., KT-10 Wilms tumor)." (PMID 36362482, 2022). "We have tested multiple commercially available and patient-derived un-methylated MGMT glioblastoma lines from our collaborators but failed to form MGMT protein-expressing brain tumors after orthotropic inoculation in athymic rats (data not shown)." (PMID 33850305, 2022). "Specifically, we analyzed EIF4EBP1 mRNA expression levels in EGFR-amplified and EGFR-non-amplified as well as in O6-methylguanine DNA methyltransferase (MGMT) promoter-methylated and promoter-unmethylated IDH-wildtype glioblastoma patient samples using publically available datasets." (PMID 35228525, 2022). "Here, we aim to analyze the prognostic impact of obesity in glioblastoma with or without MGMT methylation using two well-characterized study cohorts." (PMID 35704157, 2022). "Since glioblastoma patients without MGMT promoter methylation are resistant to temozolomide and have a worse prognosis, the treatment strategy depends on MGMT promoter methylation status." (PMID 35397757, 2022). "Since patients with glioblastoma without MGMT promoter methylation are resistant to temozolomide and have a poor prognosis, the treatment strategy depends on the MGMT promoter methylation status." (PMID 36291588, 2022). "One major limitation of the current studies is the lack of MGMT-expressing glioblastoma xenograft models." (PMID 33850305, 2022). "The sensitivity of the TMZ-resistant glioblastoma cell line to metformin might be mediated via the suppression of mitochondrial biogenesis, EMT, and MGMT expression." (PMID 35897747, 2022). "CheckMate-548, which compared nivolumab or placebo with radiotherapy plus temozolomide (TMZ) in patients with newly diagnosed glioblastoma with a methylated MGMT promotor, obtained a negative result." (PMID 35204029, 2022). "This analysis of two study cohorts provides evidence for a negative prognostic impact of obesity in MGMT-methylated glioblastoma, but not in MGMT-unmethylated glioblastoma." (PMID 35704157, 2022). "Valganciclovir was safe to use and prolonged median survival after recurrence for patients with recurrent glioblastoma, re-operated or not after recurrence, and with methylated or unmethylated MGMT promoter gene." (PMID 35454863, 2022). "REP was significantly more likely after STR and in IDH wild-type versus IDH mutant glioblastomas, but was not influenced by MGMT status." (PMID 35769410, 2022). "As the major anti-CMV treatment, valganciclovir has demonstrated a promising survival benefit in both newly diagnosed and recurrent glioblastoma as an adjuvant therapy, regardless of surgery and the MGMT promoter methylation state." (PMID 36079151, 2022). "Our data showed that metformin could suppress MGMT expression in TMZ-resistant glioblastoma cells (LN229 (+IRL) TMZ-R), suggesting that it can be repurposed to overcome TMZ resistance in glioblastoma tissue." (PMID 35897747, 2022).
glioblastoma (continued). "Moreover, in glioblastoma CSCs, epigallocatechin gallate (EGCG) treatment downregulated P-gp overexpression but not that of ABCG2 or O6-methylguanine-DNA methyltransferase (MGMT) and increased the cytotoxic effect of TM." (PMID 36627897, 2022). "Meanwhile, patients with MGMT promoter methylation, observed in 30% to 50% of IDH-WT glioblastoma, may present better prognosis and treatment response." (PMID 35135556, 2022). "Taken together these results support a hypothesis where downregulation of MGMT and accumulation of DNA damage in S-phase of combination treated TMZ-resistant glioblastoma cells serve to activate homologous recombination pathway." (PMID 36619857, 2022). "Moreover, we previously found heterogeneous MGMT methylation in the only glioblastoma IDH-mutant, WHO (2016) grade IV patient in a cohort of 12 glioblastomas, WHO (2016) grade IV22." (PMID 35701666, 2022). "While it does not factor into tumor classification, methylation of the O6-methylguanine-DNA methyltransferase (MGMT) gene promotor is a favorable prognostic factor in patients with glioblastoma." (PMID 36428546, 2022). "Although successful in predicting glioblastoma response to temozolomide, the methylation-sensitive high-resolution melt has not been validated for investigating MGMT methylation in clinical settings, thus still lacking cut-off thresholds." (PMID 35806153, 2022). "Furthermore, higher grade, IDH-wild type, non-1p19q codeletion, ATRX-wild type, MGMT unmethylated, TERT mutant, and glioblastoma were correlated with a higher CRGRS." (PMID 36267281, 2022). "We recently showed that the methylation subclass, according to the largest existing methylation-based classifier, differs within single adult-type glioblastoma (GBM) tumours, and that the MGMT promoter methylation status, a prognostic and therapy predictive biomarker, also varied intratumourally." (PMID 35842717, 2022). "Therefore, the effects of Cyn were assessed on two patient-derived glioblastoma cell lines, NULU and ZAR, genetically characterized by IDH1/2 wild-type and unmethylated MGMT gene promoter, thus by a TMZ-resistant phenotype." (PMID 35884887, 2022). "TMZ is a significant part of the standard therapy of almost all glioblastoma and HGA, but TMZ might be of limited use in tumors with the unmethylated MGMT promoter." (PMID 35563629, 2022). "In another Phase III trial (CheckMate 498), nivolumab combined with radiotherapy also failed to prolong survival in patients with newly diagnosed MGMT-unmethylated glioblastoma compared with the SOC." (PMID 35406398, 2022). "According to the current results, mifepristone could contribute to the modulation of tumor relapse in glioblastoma by decreasing the levels of VEGF, MGMT, and P-gp." (PMID 33680961, 2021). "Seven of the glioblastoma patients were negative for O6-methylguanine-DNA methyltransferase (MGMT) promoter methylation, four were positive for methylation, and five were not tested." (PMID 34867723, 2021). "Over-expression of O6-methylguanine methyltransferase (MGMT) and/or lack of a DNA repair pathway in multiple glioblastoma multiforme (GBM) cell lines are common features of refractoriness or acquired resistance of patients to TMZ chemotherapy." (PMID 34946686, 2021). "In addition, UA demonstrated greater cytotoxicity than conventional chemotherapeutics like TMZ in spite of inactivity towards O-6-methylguanine-DNA methyltransferase (MGMT), which is a known player in TMZ-resistant glioblastomas." (PMID 33925641, 2021). "The present study provides evidence that MFA as a gap junction inhibitor enhances glioblastoma cells’ vulnerability to lomustine-induced cell death independent of MGMT promoter methylation status." (PMID 33673490, 2021).